OXT (oxytocin/neurophysin I prepropeptide)
Diseases named in the same sentence as OXT in open-access papers (continued):
Sharing a sentence is not in itself a finding about the gene and the disease.
Hyponatremia (4 papers, 2021 to 2025). An abnormally decreased sodium concentration in the blood. "Of note, patients later diagnosed with SIADH-related hyponatremia, on the contrary, exhibited a significant increase of OXT secretion at 4 days after surgery." (PMID 33506439, 2021). "If OXT also contributes to hyponatremia, one can posit a chain of events passing through an induced secondary release of ANP that would also take some time to accentuate the delayed hyponatremia." (PMID 33506439, 2021). "While OXT excretion remained stable in patients who presented a normonatremic postoperative course, patients who were later diagnosed with SIADH-related hyponatremia presented with a significantly increased urinary secretion of OXT 4 days after surgery." (PMID 33506439, 2021). "Finally, in recent works, we observed an increased urinary secretion of OXT in patients later developing SIAD-related hyponatraemia after TPS and correlated this increase in secretion with patients’ natriuresis." (PMID 39681826, 2025). "Nevertheless, the 3-day lag time between the elevation of OXT on D4 and the hyponatremia on D7 could be explained by the respective mechanisms of action of AVP and OXT leading to the excretion of water and sodium." (PMID 33506439, 2021). "We were then interested to know whether the dynamics of OXT secretion was altered in patients later presenting with hyponatremia." (PMID 33506439, 2021). "The likelihood of a hypothetical secondary causal contribution of OXT in the occurrence of hyponatremia is however reduced by the absence of any observed relative increase of urinary OXT on D7 in the hyponatremic patients." (PMID 33506439, 2021). "OXT excretion however becomes abnormally high on or around 4 days after surgery in patients later developing hyponatremia, suggesting that this abnormal dynamics of OXT secretion might serve as an early marker for transsphenoidal surgery-related hyponatremia attributed to SIADH." (PMID 33506439, 2021). "Furthermore, this abnormal OXT excretion preceded hyponatremia, suggesting that the abnormal dynamics of OXT secretion might serve as an early marker for the diagnosis of transsphenoidal surgery-related hyponatremia." (PMID 33506439, 2021). "However, we observed that OXT secretion becomes abnormally high in patients later diagnosed with SIADH-related hyponatremia, suggesting the existence of a SIOXT and a potential contributing role for this hormone in SIADH-associated hyponatremia." (PMID 33506439, 2021). "Indeed, abnormal OXT secretion concomitant to SIADH might also contribute to sodium imbalance and therefore to hyponatremia." (PMID 33506439, 2021). "Interestingly, while no specific dynamics of OXT excretion were noted when patients remained normonatremic, we observed that urinary output of OXT significantly increased 4 days after surgery in patients later diagnosed with SIADH-related hyponatremia." (PMID 33506439, 2021).
Prader-Willi syndrome (4 papers, 2022 to 2023). "Post-mortem human hypothalamic tissues from patients with Prader-Willi syndrome (PWS) have demonstrated a reduced number and volume of OXT neurons in the paraventricular nucleus in comparison with controls." (PMID 35795430, 2022).
psychosis (4 papers, 2019 to 2023). "First, our results showed increased OXT and OXTR in the placentas of women who underwent a first episode of psychosis during pregnancy." (PMID 37373400, 2023).
anorexia nervosa (3 papers, 2020 to 2024). A disorder most often seen in adolescent females characterized by a refusal to maintain a minimally normal body weight, an intense fear of gaining weight, a disturbance in body image, and, in postmenarcheal females, the development of amenorrhea. "OXT regulation plays an important role also in metabolic diseases, and anorexia nervosa (AN) is one of these." (PMID 32438751, 2020). "Also, in metabolic diseases such as anorexia nervosa, OXT regulation is critical." (PMID 32438751, 2020).
colitis (3 papers, 2021 to 2024). Inflammation of the colon. "Hypothalamic OXT-producing neurons was also found to suppress colitis-associated colorectal cancer." (PMID 36045118, 2022). "In summary, our study provides comprehensive evidence highlighting the crucial role of OXT in maintaining colon homeostasis and protecting against colitis and CAC tumorigenesis." (PMID 38979515, 2024). "This study aimed to uncover the essential function of OXT signaling in colonic carcinogenesis and colitis." (PMID 38979515, 2024). "Having established that mice with OXTR deficiency in intestinal epithelium exhibit more advanced colitis and colon cancer, we further investigated the role of the OXT system in CAC through OXT supplementation." (PMID 38979515, 2024). "In this study, we present compelling evidence supporting the involvement of OXT in the formation of colonic mucus and its protective role in colitis and CAC tumorigenesis." (PMID 38979515, 2024). "To understand how OXT signaling modulates the pathogenesis of DSS-induced colitis, we evaluated the expression levels of colonic barrier proteins in OXTRfl/fl and OXTR△IEC IECs with or without DSS treatment." (PMID 38979515, 2024). "Moreover, our analysis of human colitis and CAC samples reveals down-regulation of OXTR expression, indicating complex and context-dependent roles of OXT signaling under these conditions." (PMID 38979515, 2024). "Our previous studies have already demonstrated the beneficial effects of OXT in mitigating DSS-induced intestinal injury by inducing prostaglandin E2 release, as well as its regulatory roles in macrophage polarization, and dendritic cell tolerance to alleviate DSS-induced colitis." (PMID 38979515, 2024). "Notably, we hypothesize that neoplastic lesions in colitis, unlike sporadic colon cancer, may largely operate independently of Wnt signaling, warranting further investigation into the specific function of OXT signaling in Wnt-driven colon cancer." (PMID 38979515, 2024).
craniopharyngioma (3 papers, 2023 to 2025). A benign, partly cystic, epithelial tumor of the sellar region, presumably derived from Rathke pouch epithelium. "In a separate study of individuals with craniopharyngioma, the change in salivary OXT in response to meals and exercise appeared to be related to BMI and eating behaviors, thereby demonstrating a potential utility of OXT in HO." (PMID 37780616, 2023). "•Patients with craniopharyngioma may develop oxytocin (OXT) insufficiency." (PMID 39622476, 2025). "Clinical trials of intranasal OXT in pediatric disorders have focused primarily on PWS, ASD, and hypothalamic obesity after craniopharyngioma." (PMID 41614746, 2025).
dementia (3 papers, 2019 to 2025). Loss of intellectual abilities interfering with an individual's social and occupational functions. "Conversely, we observed OXT hypermethylation in the DNA from peripheral blood of participants who progressed to dementia." (PMID 31775875, 2019).
Hyperglycemia (3 papers, 2020 to 2024). An increased concentration of glucose in the blood. "We found that hyperglycemia suppresses the expression of both OXT and OXTR, and OXTR expression remains low, while OXT expression returns to normal during subsequent normoglycemia." (PMID 33633538, 2021).
insomnia (3 papers, 2022 to 2025). A sleep disorder characterized by difficulty in falling asleep and/or remaining asleep. "A previous study showed that intranasal OXT significantly increased plasma OXT concentrations within 40 min; thus, we supposed that intranasal oxytocin—a method already proven safe and used for many years —could probably be used to modulate cardiovascular disease in patients with insomnia." (PMID 40699619, 2025).
Insulin resistance (3 papers, 2013 to 2022). Increased resistance towards insulin, that is, diminished effectiveness of insulin in reducing blood glucose levels. "Our data proved that OXT and its analogs have the actions to reverse insulin resistance and improve insulin secretion in these mouse models." (PMID 23700406, 2013).
ischemia (3 papers, 2022 to 2024). A hypoperfusion of the BLOOD through an organ or tissue caused by a PATHOLOGIC CONSTRICTION or obstruction of its BLOOD VESSELS, or an absence of BLOOD CIRCULATION. "The neuroprotective effect of 1 μM OXT was also reported in an ischemia model consisting of exposure to OGD of hippocampal slices from 7 to 10-day-old rat pups, resembling hypoxic-ischemic lesions." (PMID 38921042, 2024). "Recently, the same strain of rats was used in a study where the activation of cardiac mast cells and other inflammatory factors participated in the protective activity of OXT in an ischemia/reperfusion injury model." (PMID 36358953, 2022). "In another type of cells, the heart-derived H9c2 cells, OXT treatment in ischemia/reperfusion was more effective in early reperfusion." (PMID 36358953, 2022). "Our results suggest that OXT might activate neuroprotective mechanisms in the developing neurons at DIV7 impacted by severe ischemia." (PMID 38921042, 2024). "In addition to OXT network activation and VNS, parasympathetic-mediated cardioprotection, particularly following ischemia reperfusion, is likely complex and may involve both vagus-dependent and independent mechanisms." (PMID 37801130, 2023).
mood disorder (3 papers, 2018 to 2024). A cognitive disorder a disturbance in which the person's mood is hypothesized to be the main underlying feature. "OXT is a neurotransmitter or neuromodulator with central actions in the limbic system, especially the amygdala, an essential structure in mood disorders." (PMID 37520225, 2023).
neuroblastoma (3 papers, 2017 to 2024). Neuroblastoma (NB) is the most common solid, extracranial childhood tumor. "Our results suggest that OXT protects dopaminergic neuroblastoma cells from CORT-induced DA dysfunction, potentially through the involvement of oxytocin receptors and the PKA/CREB signaling pathway." (PMID 39607552, 2024). "The inhibitory effect of OXT on Crh gene expression in rodent PVN and neuroblastoma cells expressing Oxtr supports this observation." (PMID 36817409, 2022).
osteoarthritis (3 papers, 2023 to 2024). A noninflammatory degenerative joint disease occurring chiefly in older persons, characterized by degeneration of the articular cartilage, hypertrophy of bone at the margins and changes in the synovial membrane. "OXT also stimulates the stem cell chondrogenic differentiation, making this molecule an interesting candidate for osteoarthritis treatment: in fact, in hBM-MSCs and hASCs, OXT enhances the mRNA expression of genes involved in chondrogenesis." (PMID 37445991, 2023). "The relationship between OXT and chondrogenesis was investigated in a recent study aimed at understanding whether OXT plays a role in osteoarthritis (OA)." (PMID 39590307, 2024).
Parkinson disease (3 papers, 2023 to 2025). A progressive degenerative disorder of the central nervous system characterized by loss of dopamine producing neurons in the substantia nigra and the presence of Lewy bodies in the substantia nigra and locus coeruleus. "Interestingly, the effect of OXT has been confirmed in various diseases, including myocardial ischemia-reperfusion injury and Parkinson’s disease." (PMID 40143166, 2025).
stress-related disorder (3 papers, 2020 to 2025). Stress-related disorders are mental health disorders that are a result of an atypical response to both short and long-term anxiety due to physical, mental, or emotional stress. "The hypothalamic peptide hormone oxytocin (OXT) has been increasingly recognized as a promising therapeutic candidate for stress-related disorders such as major depressive disorder and PTSD due to its role in stress regulation and social behavior." (PMID 32848947, 2020).
Stroke (3 papers, 2020 to 2025). Sudden impairment of blood flow to a part of the brain due to occlusion or rupture of an artery to the brain. "Consistent with our findings, a previous study reported that OXT upregulated Bcl-2 expression in a mouse stroke model." (PMID 40143166, 2025). "Only one human case study post-stroke has been published, wherein the authors speculated that a patient’s rapid recovery from post-partum stroke may have been due to OXT administered to reduce postpartum bleeding and increased endogenous OXT release upon contact with her newborn." (PMID 33071746, 2020).
virus infection (3 papers, 2017 to 2024). "The expression profile analysis revealed many interesting genes that may be associated with the viral infection process (such as OXT and a number of genes implicated in the Toll Like Receptors signaling network and complement pathway)." (PMID 34203742, 2021).
amnesia (2 papers, 2015 to 2023). Pathologic partial or complete loss of the ability to recall past experiences ( AMNESIA, RETROGRADE) or to form new memories ( AMNESIA, ANTEROGRADE). "In addition, Ferguson and colleagues demonstrated social amnesia in OXT knockout mice, but OXT intracerebroventricular injections were able to restore social memory, whereas treatment with an OXT-antagonist induced social-amnesia in mice with an intact OXT system." (PMID 36979271, 2023).
attention deficit-hyperactivity disorder (2 papers, 2016 to 2025). A disorder characterized by a marked pattern of inattention and/or hyperactivity-impulsivity that is inconsistent with developmental level and clearly interferes with functioning in at least two settings (e.g. at home and at school). "Recently, we have studied serum oxytocin (OXT) levels in pediatric patients with Attention Deficit/Hyperactivity Disorder (AD/HD)." (PMID 27536785, 2016).
binge eating disorder (2 papers, 2022 to 2024). Recurrent episodes of over-eating. "Although not yet confirmed for BED, significant associations have been observed between the G-T-A-G haplotype of the OXT gene and the preference for eating foods rich in fats and sugars and, therefore, having a particular sensitivity to binge eating disorders." (PMID 39057584, 2024). "OXT functioning is altered in patients with eating and weight disorders, and a variant of the oxytocin receptor gene (OXTR) has been associated with impulsive eating behavior as it is seen in patients with binge eating disorder (BED)." (PMID 36042529, 2022).
cognitive decline (2 papers, 2020 to 2025). "Intravenous tail vein administration of OXT in group‐housed 12‐week‐old APP/PS1 mice reduced age‐associated Aβ deposition and neuronal apoptosis, alleviated cognitive decline." (PMID 40635450, 2025). "OXT and artificially developed OXTR agonists have potential as a therapeutic agent to improve the cognitive decline associated with HFD." (PMID 32719656, 2020).
colon cancer (2 papers, 2019 to 2024). "OXT (0.1 nM) significantly reduced the Transwell number of colon cancer cell line, Ls174t and SW480 cells." (PMID 31920487, 2019). "The present Matrigel invasion study also confirms that OXT significantly inhibits the migration of colon cancer cells, which is mediated by OXTR." (PMID 31920487, 2019). "Moreover, cell invasion experiment showed that OXT treatment reduced the invasion ability of colon cancer cells and blocking OXTR with atosiban blocked OXT-reduced invasion ability of human colon cancer cell lines Ls174T and SW480." (PMID 31920487, 2019). "Importantly, blocking OXTR activation inhibited OXT-induced reduction of colon cancer cell migration in both types of colon cancer cell lines." (PMID 31920487, 2019). "Additionally, using Transwell migration assay, we observed effects of OXT with and without OXTR antagonist on the migration of colon cancer cells." (PMID 31920487, 2019).
colorectal cancer (2 papers, 2019 to 2022). A primary or metastatic malignant neoplasm that affects the colon or rectum. "Colorectal cancer development is associated with the reduction of OXTR signaling since OXT can suppress FAPα and CCL-2 expressions and their associated CAC migration via OXTR." (PMID 31920487, 2019). "Interestingly, stimulation of hypothalamic OXT neurons inhibited the progression of colorectal cancer in mice." (PMID 36172369, 2022). "Thus OXT may be a new strategy for the treatment of colorectal cancer." (PMID 36172369, 2022).
Delusion (2 papers, 2018 to 2020). A delusion is a fixed false belief held despite evidence to the contrary. "The authors suggested OXT to promote self-referential bias in patients with delusions or, alternatively, an increased OXT secretion in response to distress related to social-cognitive bias." (PMID 32255800, 2020). "A significant correlation between social cognitive capacity and OXT plasma levels was only found in patients with delusions." (PMID 29740360, 2018).
developmental delay (2 papers, 2016 to 2017). "In summary, this is the first study to demonstrate association of CD157 with neonatal developmental delay in communicative ability, which could be rescued by exogenous OXT administration." (PMID 28566999, 2017).
dystocia (2 papers, 2010 to 2023). Slow or difficult obstetric labor or childbirth. "The association between OXT and dystocia is due to the effect that OXT has on the intensity and duration of myometrial contractions, reducing uterine blood flow and fetal oxygenation." (PMID 36830555, 2023). "Initially, we sequenced all OXT and OXTR exons including splice sites and putative promoter regions in five individuals with dystocia and one control to detect common variations." (PMID 20587075, 2010).
emotional dysregulation (2 papers, 2025). "Furthermore, reduced basal levels of OXT cause the amygdala to become more activated in BPD patients, impairing their ability to comprehend social cues and resulting in aberrant behaviors and emotional dysregulation (Perez-Rodriguez, Derish, & New, 2014)." (PMID 40114597, 2025).
epilepsy (2 papers, 2022 to 2025). A brain disorder characterized by episodes of abnormally increased neuronal discharge resulting in transient episodes of sensory or motor neurological dysfunction, or psychic dysfunction. "This suggests the possibility of maternal administration of OXT may reduce the risk of postnatal development of ASD, even when epilepsy patients are medicated with anticonvulsants including VPA during pregnancy." (PMID 35432011, 2022).
glioblastoma (2 papers, 2023 to 2025). The most malignant astrocytic tumor (WHO grade IV). "Previous research has demonstrated that OXT promotes the proliferation of the glioblastoma cell line U-87MG through activation of pERK1/2 protein expression." (PMID 40143166, 2025).
Huntington disease (2 papers, 2018 to 2022). Huntington disease (HD) is a rare neurodegenerative disorder of the central nervous system characterized by unwanted choreatic movements, behavioral and psychiatric disturbances and dementia. "Summary of oxytocin (OXT) results in Huntington’s disease (HD)." (PMID 36187357, 2022).
intellectual disabilities (2 papers, 2017 to 2020). "Individuals with PWS also manifest intellectual disabilities, with their numbers of PVN-OXT neurons reduced and levels of circulating OXT decreased." (PMID 32438751, 2020).
leukemia (2 papers, 2012 to 2017). A malignant (clonal) hematologic disorder, involving hematopoietic stem cells and characterized by the presence of primitive or atypical myeloid or lymphoid cells in the bone marrow and the blood. "With respect to OXT, we reported that CD38, a type II transmembrane protein, which controls leukemia malignancy in blood cells, is expressed in the brain and required for OXT secretion in mice." (PMID 23335873, 2012).
memory impairment (2 papers, 2023 to 2025). "This work provides novel insights into the critical role of OXT in REM sleep-mediated social memory consolidation and highlights its therapeutic potential in addressing memory impairments caused by sleep disturbances." (PMID 40093885, 2025). "Recently, we reported that OXT reverses learning and memory impairment in AD animal models." (PMID 37887270, 2023).